RIF1 (replication timing regulatory factor 1)
Description:
Key regulator of TP53BP1 that plays a key role in the repair of double-strand DNA breaks (DSBs) in response to DNA damage: acts by promoting non-homologous end joining (NHEJ)-mediated repair of DSBs. In response to DNA damage, interacts with ATM-phosphorylated TP53BP1. Interaction with TP53BP1 leads to dissociate the interaction between NUDT16L1/TIRR and TP53BP1, thereby unmasking the tandem Tudor-like domain of TP53BP1 and allowing recruitment to DNA DSBs. Once recruited to DSBs, RIF1 and TP53BP1 act by promoting NHEJ-mediated repair of DSBs. In the same time, RIF1 and TP53BP1 specifically counteract the function of BRCA1 by blocking DSBs resection via homologous recombination (HR) during G1 phase. Also required for immunoglobulin class-switch recombination (CSR) during antibody genesis, a process that involves the generation of DNA DSBs (By similarity). Promotes NHEJ of dysfunctional telomeres (By similarity).
Synonyms: FLJ12870; FLJ10599
Tractability: Antibody: its Gene Ontology location is reachable by antibodies, with high confidence. PROTAC: ubiquitination databases record sites on it; its protein half-life has been measured.
Gene: Protein-coding gene on chromosome 2 (151,409,883 to 151,508,013, forward strand). Ensembl gene ENSG00000080345.
Subcellular location: Nucleus; Chromosome; Chromosome, telomere; Cytoplasm, cytoskeleton, spindle
Subcellular location (Human Protein Atlas): Nucleoplasm; Nuclear membrane; Plasma membrane
Pathways (Reactome):
DNA Repair: Nonhomologous End-Joining (NHEJ)
Gene Ontology:
Molecular function: protein binding
Biological process: DNA damage response; negative regulation of double-strand break repair via homologous recombination; positive regulation of double-strand break repair via nonhomologous end joining; telomere maintenance in response to DNA damage; negative regulation of gene expression, epigenetic; negative regulation of transcription by RNA polymerase II; positive regulation of isotype switching; subtelomeric heterochromatin formation; telomere maintenance
Cellular component: condensed chromosome; nuclear membrane; nucleoplasm; nucleus; site of double-strand break; spindle midzone; chromatin; chromosome, telomeric repeat region; chromosome; chromosome, telomeric region; female pronucleus; male pronucleus; spindle
Genetic constraint (gnomAD): Loss-of-function variants: 27 observed, 146.72 expected, observed/expected ratio (o/e) 0.18, 90% interval 0.14 to 0.25. The upper end of that interval is the gene's LOEUF score, 0.25, which puts it in group 1 of 6, group 1 being the genes least tolerant of losing a copy. Missense variants: 2,267 observed, 2,180.1 expected, observed/expected ratio (o/e) 1.04, 90% interval 1 to 1.08. Synonymous variants: 809 observed, 760.37 expected, observed/expected ratio (o/e) 1.06, 90% interval 1 to 1.13.
Homologues: Orthologues: chimpanzee RIF1 (99% identical), macaque RIF1 (95% identical), pig RIF1 (80% identical), dog RIF1 (79% identical), rabbit RIF1 (77% identical), guinea pig RIF1 (72% identical), rat Rif1 (70% identical), mouse Rif1 (70% identical), tropical clawed frog rif1 (44% identical), zebrafish rif1 (35% identical), Drosophila melanogaster Rif1 (12% identical), Caenorhabditis elegans rif-1.1 (8% identical), and 1 more.
Diseases named in the same sentence as RIF1 in open-access papers:
RIF1 is named in the same sentence as 49 diseases in open-access papers, as found by Europe PMC text mining. Sharing a sentence is not in itself a finding about the gene and the disease. The quoted sentences say what the papers report.
breast carcinoma (10 papers, 2013 to 2025). "To assess whether inclusion of Exon 31 is linked to overall expression level of RIF1 in the different breast cancer subtypes, we plotted PSI values for Exon 31 against total RIF1 mRNA expression in tumour samples." (PMID 40806439, 2025). "RIF1 (3.78-fold increase) has been implicated in a wide variety of cellular processes in mammals, including pluripotency of stem cells, response to double-strand breaks, and breast cancer development." (PMID 23383159, 2013). "We find, moreover, that receptor-positive breast cancers have a generally higher propensity to exclude short exons, including Exon 31 of RIF1." (PMID 40806439, 2025). "Upregulation of RIF1 in breast cancer tissues has been reported and the knockdown of RIF1 reduced cell growth and increased susceptibility of uterine cervical cancer cells to cisplatin." (PMID 37548940, 2024). "Wang showed a high expression of RIF1 in human breast carcinoma cells positively correlated with differentiation status of invasive ductal breast tumors." (PMID 34768871, 2021). "In the field of cancer research, RIF1 was reported upregulated in breast cancer and cervical cancer." (PMID 30075819, 2018). "In the field of cancer research, RIF1 was reported upregulated in breast cancer tissues and we previously found that RIF1 knockdown decreased cell growth and increased cisplatin sensitivity of cervical cancer cells." (PMID 30075819, 2018). "For basal breast cancer, the RNA processing pattern of the RIF1 transcript was unexpected." (PMID 40806439, 2025). "Therefore, the retention of RIF1 Exon 31 in this tumour type contrasts with its behaviour in the receptor-positive breast cancers, where it tends to be excluded along with other Cancer-Altered Short exons." (PMID 40806439, 2025). "Considering that RIF1 Exon 31 is itself relatively short at 78 nucleotides, we sought to extend our analysis by comparing the observed changes in RIF1 splicing to general splicing changes occurring in the different breast cancer subtypes." (PMID 40806439, 2025). "Rather, basal breast cancer showed no change in RIF1 splice variant expression when comparing matched normal and tumour samples, continuing to express the RIF1 variants in proportions similar to those in normal tissue." (PMID 40806439, 2025). "RIF1 also exhibits distinct splicing patterns, particularly in specific breast cancer subtypes." (PMID 40806439, 2025). "For basal breast cancer patients, we, however, saw no significant change in the proportion of RIF1 splice variants expressed." (PMID 40806439, 2025). "While several studies have reported changes in RIF1 expression levels in cancer or in cancer cell lines, to our knowledge this is the first study to examine RIF1 splicing in stratified cancer subtypes or indeed to report on length-based exon splicing patterns in breast cancer subtypes." (PMID 40806439, 2025). "Considering changes in RIF1 splice variant expression in the different breast cancer subtypes, we found that LumA, LumB, and HER2E breast cancers showed a significantly decreased proportion of RIF1-L transcript, in line with our observation for all breast cancer subtypes combined." (PMID 40806439, 2025). "Furthermore, Rif1 may act as an anti-checkpoint shield in repairing defective double-strand breaks (DSB) of DNA in breast cancer, and inhibition of its expression sensitizes cancer cells to drugs." (PMID 37548940, 2024). "In addition, RIF1 has been reported overexpressed in breast cancer tissues and we previously found that RIF1 knockdown could decrease cell growth and increase cisplatin sensitivity of cervical and ovarian cancer cells." (PMID 30237512, 2018). "Similarly, elevated levels of Rif1 were found in breast cancer and teratocarcinomas." (PMID 27004475, 2016). "In Luminal A (LumA), Luminal B (LumB), and HER2-enriched breast cancers (HER2E), RIF1 Exon 31 tends to be excluded, favouring RIF1-Short expression and correlating with poorer clinical outcomes." (PMID 40806439, 2025).
breast carcinoma (continued). "The results show that, while all methods were able to identify breast cancer relevant regulators, only RIF1 and RIF2 identified regulators with direct connections to ER+ breast cancer." (PMID 29741575, 2018). "RIF1 detected LRIG1, a gene that is known to correlate with relapse-free survival in ERα-positive breast cancer." (PMID 29741575, 2018). "Therefore, a breast cancer chemosensitivity study, similar to the one undertaken for NSCLC, would be useful for understanding the relationship between RIF1 expression and tumour response to chemotherapy." (PMID 40806439, 2025). "RIF1 Exon 31 is therefore behaving unusually in basal breast cancer in not showing a significant shift towards exon exclusion." (PMID 40806439, 2025). "The previous report of increased expression of RIF1 in breast tumour sections did not examine the differences between the breast cancer subtypes." (PMID 40806439, 2025). "Interestingly, we observed mutant protein expression of Replication Timing Regulatory Factor 1 (RIF1) and Torsin-1A-interacting protein 1 (TOR1AIP1) across all four breast cancer cell lines." (PMID 33274046, 2020). "Surprisingly, however, in basal breast cancer, RIF1 Exon 31 is not consistently excluded, which may impact prognosis since RIF1-Long protects against replication stress." (PMID 40806439, 2025). "Therefore, total RIF1 mRNA levels do not appear to predict preferential expression of a specific RIF1 isoform in breast cancer." (PMID 40806439, 2025). "However, for basal breast cancer, RIF1 Exon 31 is not within the cohort of Cancer-Altered Short exons, because with a ΔPSIav value of 0.02, its level of inclusion is only marginally changed in basal cancer compared to normal tissue (since its ΔPSIav lies between −0.1 and 0.1)." (PMID 40806439, 2025). "We find this same tendency to exclude RIF1 Exon 31 in LumA, LumB, and HER2E breast cancers, although not in basal breast cancer." (PMID 40806439, 2025).
ovarian carcinoma (6 papers, 2015 to 2024). A malignant neoplasm originating from the surface ovarian epithelium. "Because platinum-based chemotherapeutics utilize double-stranded breaks to cause cell death, overexpression of RIF1 in ovarian cancer would reverse any damage done by chemotherapeutics; therefore, its potential to be a therapeutic target is promising." (PMID 36551731, 2022). "Further investigations should also focus on the impact of Rif1 and telomeres on the survival rate and specific ovarian cancer subtypes and different FIGO stages since these are still research gaps that require further elucidation." (PMID 37548940, 2024). "In this review, we aim to shed light on the importance of the relationship between telomere biology and the RIF1 protein during cancerogenesis, especially during the development of ovarian cancer in women." (PMID 37548940, 2024). "In this review, we provide an update of recent literature to elucidate the relation between telomere biology and the RIF1 protein during the development of ovarian cancer in women." (PMID 37548940, 2024). "RIF1 promotes the growth and development of human epithelial ovarian cancer by activating the reverse transcriptase of telomerase." (PMID 36110943, 2022). "By analyzing the data from the publicly available TCGA database, we found that the mRNA expression levels of RIF1 positively correlated with hTERT expression level in ovarian cancer tissues." (PMID 30075819, 2018). "Gene set enrichment analysis (GSEA) indicated that RIF1 expression closely correlated with the expression of a set of stemness regulating genes in the publicly available ovarian cancer patient expression profiles (GSE7463)." (PMID 30075819, 2018). "By performing Gene set enrichment analysis (GSEA) in the GEO ovarian cancer data set, we found that the RIF1 expression level was positively correlated with TERT-activated gene signatures and TERT downstream PI3K/AKT signaling (GSE7463)." (PMID 30075819, 2018). "To investigate the clinical relevance of RIF1 expression in ovarian cancer patients, we first examined RIF1 protein expression in ovarian cancer tissues, benign tissues and normal ovarian tissues by immunohistochemistry." (PMID 30075819, 2018). "RIF1 expression in ovarian cancer, benign and normal ovarian tissues was examined by immunohistochemistry." (PMID 30075819, 2018). "We found that RIF1 expression level in ovarian cancer cell lines were obviously higher than the normal ovarian epithelial cell line." (PMID 30075819, 2018). "Consistently, in the Oncomine database, RIF1 mRNA level was higher in ovarian cancer tissues than that in normal ovarian tissues (P < 0.001)." (PMID 30075819, 2018). "Significantly higher expression levels of RIF1 were observed in ovarian cancer tissues compared with benign and normal ovarian tissues." (PMID 30075819, 2018). "Additionally, analysis of epithelial ovarian cancer tissue revealed that nearly two out of three patients with chemoresistant epithelial ovarian cancer had high expression of RIF1, whereas only 34.2% of chemosensitive patients displayed overexpression of RIF1." (PMID 36551731, 2022). "Correlation between the RIF1 expression and the clinical features of ovarian cancer patients." (PMID 30075819, 2018). "Moreover, the expression of RIF1 is positively correlated with hTERT expression in ovarian cancer tissues in two separate gene expression profiles from TCGA database and our own EOC tissue samples." (PMID 30075819, 2018). "Actually, the relationship between human RIF1 and hTERT as well as the role of RIF1 in ovarian cancer progression is still unknown." (PMID 30075819, 2018). "However, detailed knowledge regarding the interplay between RIF1 and telomeres and their degree of engagement in epithelial ovarian cancer (EOC) is still elusive, despite the fact that such knowledge could be of relevance in clinical practice to find novel biomarkers." (PMID 37548940, 2024).
ovarian carcinoma (continued). "Replication timing regulatory factor 1 (RIF1) and DNA-dependent protein kinase (DNA-PK) are involved in the NHEJ pathway, and both have implications for ovarian cancer drug resistance." (PMID 36551731, 2022). "And then, we detected the mRNA and protein expression levels of RIF1 in normal ovarian epithelial cell line (IOSE80) and two human epithelial ovarian cancer cell lines (OVCAR3 and A2780)." (PMID 30075819, 2018). "All in all, there is no doubt that both RIF1 and telomeres do play a critical role during the pathogenesis of ovarian cancer in women regardless of age, therefore, they can be used in clinical practice as potential diagnostic and prognostic biomarkers." (PMID 37548940, 2024). "We found that RIF1 had a positive strong expression in ovarian cancer, and negative weak staining in normal ovary." (PMID 30075819, 2018). "However, in breast and ovarian cancer cells with BRCA1 deficiency, 53BP1 signaling in the S/G2 phases is no longer inhibited, and RIF1 and PTIP translocate to DNA break sites via binding to phosphorylated 53BP1 to protect DNA ends from processing." (PMID 27462418, 2015). "Moreover, we intend to answer the question of whether TERT or RIF1 could be established as new biomarkers for the early detection of ovarian cancer regardless of the patient’s age." (PMID 37548940, 2024).
lung carcinoma (5 papers, 2012 to 2025). "Importantly, the RIF1 gene is mutated in some breast cancer cell lines, overexpressed in lung cancers, and positively correlates with poor prognosis in lung cancer patients." (PMID 33946274, 2021). "Overall RIF1 expression is altered in several cancer types, with increased transcript levels in colon and lung cancers." (PMID 40806439, 2025). "As RIF1 has been reported to be involved in ES self-renewal and is highly expressed in mouse ESCs21,22, we explored whether the expression of RIF1 would be related to CSC-like properties in lung cancer cells." (PMID 30237512, 2018). "The pathway analysis result suggests that the genes top-ranked by NGP-NR, the Taylor method, RIF1 and RIF2 may be associated with the different functional status of cell cycle process between lung cancer and normal samples." (PMID 22838965, 2012). "Data from The Cancer Genome Atlas (TCGA) have been used previously to investigate RIF1 expression in NSCLC, the most common lung cancer subtype." (PMID 40806439, 2025). "Of these, RIF1 expression has only been previously studied in NSCLC, the most common lung cancer subtype." (PMID 40806439, 2025). "We observed that RIF1 had a strong positive expression in lung cancer tissue samples, and negative weak staining in normal lung tissues." (PMID 30237512, 2018).
cervical cancer (4 papers, 2017 to 2020). A primary or metastatic malignant neoplasm involving the cervix. "RIF1 has been shown upregulated in breast and cervical cancer, this study intends to find out the potential effects of the expression and biological functions of RIF1 in NSCLC." (PMID 30237512, 2018). "RIF1 is upregulated at both mRNA and protein levels in clinical cervical cancer specimens, indicating its clinical significance." (PMID 29291010, 2017). "RIF1 knockdown reduced cervical cancer cell growth, colony formation, migration and epithelial–mesenchymal transition (EMT) markers." (PMID 29291010, 2017). "In this study, we explored the role of RIF1 in cervical cancer cell growth, migration and platinum-based chemotherapy." (PMID 29291010, 2017). "Since aberrant regulation of apoptosis is one of the contributing factors to cancer progression and development, we then examined the effects of RIF1 on the apoptosis of cervical cancer cells by Annexin V-FITC/PI staining assay." (PMID 29291010, 2017). "As RIF1 participates in cell cycle, apoptosis and DNA repair pathway, and all these signaling pathways are involved in the pharmacodynamics mechanism of platinum drugs, we investigated the involvement of RIF1 in sensitivity to cisplatin in cervical cancer." (PMID 29291010, 2017). "Moreover, transient RIF1 silencing using short hairpin RNA has been shown to reduce the efficiency of HeLa cervical cancer cells (which are HPV18+) to form colonies and increased their sensitivity to Cisplatin32." (PMID 32066835, 2020). "Additionally, we discovered that silencing of RIF1 greatly inhibited migration of cervical cancer cells, and found that downregulation of RIF1 significantly decreased the expression of EMT markers, such as N-cadherin, MMP2 and Integrin-β1." (PMID 29291010, 2017). "We found that the expression levels of N-cadherin, MMP2 and Integrin β1 were significantly decreased in RIF1 knockdown groups, suggesting that silencing of RIF1 might inhibit migration of cervical cancer cells by inhibiting the EMT signaling pathway." (PMID 29291010, 2017). "In terms of mechanism research, increased CDKN1A expression and Bax/Bcl-2/caspase-3 signaling pathway might be involved in the G2/M phase arrest and increased apoptosis in RIF1-silenced cervical cancer cells." (PMID 29291010, 2017). "So we explored whether RIF1 affected cervical cancer cellular DNA repair capacity upon cisplatin treatment." (PMID 29291010, 2017). "In this study, we found that RIF1 is upregulated in cervical cancer tissues compared with normal tissues both at mRNA and protein levels through online databases." (PMID 29291010, 2017). "And the function of RIF1 in cervical cancer has not been directly investigated too." (PMID 29291010, 2017).
non-small cell lung carcinoma (4 papers, 2019 to 2025). A group of at least three distinct histological types of lung cancer, including non-small cell squamous cell carcinoma, adenocarcinoma, and large cell carcinoma. "RIF1 expression has been reported as upregulated across different tumour types, including breast, cervical, ovarian, and non-small cell lung cancers." (PMID 40806439, 2025). "Exosomal circ-RACGAP1 recruiteS PTBP1 to induce RIF1 deacetylation, which then activates the Wnt/β-catenin pathway and prmotes the proliferation of non-small cell lung cancer (NSCLC) cells." (PMID 37525158, 2023). "In non-small-cell lung cancer (NSCLC), RIF1 has been found to activate WNT/β-catenin signaling by promoting the interaction between PP1 and AXIN1." (PMID 38291457, 2024).